CEACAM1 (CEA cell adhesion molecule 1)
Diseases named in the same sentence as CEACAM1 in open-access papers (continued):
Sharing a sentence is not in itself a finding about the gene and the disease.
inflammation (3 papers, 2021 to 2025). Aberrant reaction of the microcirculation characterized by movement of fluid and leukocytes from the blood into extravascular tissues. "In immune cells, CEACAM1 has been reported to inhibit T-cell activation and inflammation, which postulates the idea that hepatic inflammation observed in CEACAM1-mutant mice may have resulted from the loss of CEACAM1’s anti-inflammatory effects." (PMID 40985048, 2025). "CEACAM1 correlated with vascular inflammation in the aorta, and CEACAM1, MMP9, MPO, ERV3-1, UBALD2 and LSMEM1 correlated with vascular inflammation in the carotid arteries." (PMID 34639156, 2021). "Next, we aimed to determine whether 3′UTR:MOs targeting hepatic Ceacam1 may potentiate cytoprotective adaptive responses in a clinically relevant in vivo mouse model of sterile liver inflammation." (PMID 40985895, 2025).
metabolic disease (3 papers, 2016 to 2022). A congenital disorder (due to inherited enzyme abnormality) or acquired (due to failure of a metabolically important organ) disorder resulting from an abnormal metabolic process. "On the other hand, earlier studies indicated that CEACAM1 was also related to some metabolic diseases." (PMID 32414367, 2020).
femur (2 papers, 2016 to 2023). "OS patients with femur tumors had greater serum CEACAM1 level than OS patients with tumors at other sites, but this was not significantly different (P = 0.08, P = 0.17; respectively)." (PMID 27074014, 2016).
benign tumors (1 paper, 2020). "A 6-biomarker model (HE4, CA125, CXCL1, ITGAV, CEACAM1, IL-10RB and age) was found to be the best model for discrimination between benign tumors and EOC including borderline tumors." (PMID 33075095, 2020). "A six-biomarker model including HE4, CA125, CEACAM1, CTSV, CXCL6, S100A4 and age was found to be the best model for discriminating between benign tumors and EOC with AUC 0.921 (0.863–0.979), sensitivity 0.897 / specificity 0.889 at best point cut-off (p = 0.025)." (PMID 33075095, 2020).
digestive diseases (1 paper, 2025). "Notably, leptin (LEP), GDF15, and ADM showed the strongest associations with lung function, while BST2, THBS2, and CEACAM1 exhibited the most significant associations with digestive diseases." (PMID 40048323, 2025).
CEACAM1 also shares sentences with these, for which no sentence is quoted: celiac disease (2 papers); chronic pancreatitis (2); gastric tumors (2); Hyperglycemia (2); leukemia (2); lung squamous cell carcinoma (2); Type 2 Diabetes (2); abortion (1); acute leukemia (1); adenoma (1); alcoholic fatty liver disease (1); ankylosing spondylitis (1); basal-like breast carcinoma (1); candidiasis (1); cardiomyopathy (1); classical Hodgkin lymphoma (1); Clear Cell Renal Cell Carcinoma (1); cystadenoma (1); depression (1); dry eye (1); End Stage Liver Disease (1); endometriosis (1); fibrosis (1); follicular lymphoma (1); fungal infections (1); giant cell arteritis (1); glioblastoma multiforme (1); Glucose intolerance (1); hepatic (1); Hypercholesterolemia (1).
A further 33 diseases each share a sentence with CEACAM1 in 1 paper.